MRPL15 (mitochondrial ribosomal protein L15)
Synonyms: L15mt; MRP-L15; HSPC145; RPML7; MRP-L7; uL15m
Tractability: Small molecule: a structure with a bound ligand is known. PROTAC: ubiquitination databases record sites on it; its protein half-life has been measured.
Gene: Protein-coding gene on chromosome 8 (54,135,183 to 54,149,588, forward strand). Ensembl gene ENSG00000137547.
Subcellular location: Mitochondrion
Subcellular location (Human Protein Atlas): Mitochondria; Nucleoplasm
Pathways (Reactome):
Metabolism of proteins: Mitochondrial ribosome-associated quality control; Mitochondrial translation elongation; Mitochondrial translation initiation; Mitochondrial translation termination
Gene Ontology:
Molecular function: protein binding; RNA binding; structural constituent of ribosome
Biological process: mitochondrial translation; translation
Cellular component: mitochondrial large ribosomal subunit; mitochondrion; mitochondrial inner membrane; large ribosomal subunit
Genetic constraint (gnomAD): Loss-of-function variants: 24 observed, 27.82 expected, observed/expected ratio (o/e) 0.86, 90% interval 0.62 to 1.21. The upper end of that interval is the gene's LOEUF score, 1.21, which puts it in group 5 of 6, group 1 being the genes least tolerant of losing a copy. Missense variants: 343 observed, 371 expected, observed/expected ratio (o/e) 0.92, 90% interval 0.85 to 1.01. Synonymous variants: 124 observed, 132.37 expected, observed/expected ratio (o/e) 0.94, 90% interval 0.81 to 1.09.
Homologues: Orthologues: chimpanzee MRPL15 (100% identical), macaque MRPL15 (97% identical), dog MRPL15 (95% identical), pig MRPL15 (94% identical), rabbit MRPL15 (91% identical), mouse Mrpl15 (90% identical), rat Mrpl15 (90% identical), guinea pig MRPL15 (90% identical), tropical clawed frog mrpl15 (71% identical), zebrafish mrpl15 (69% identical), Drosophila melanogaster mRpL15 (51% identical), Caenorhabditis elegans mrpl-15 (36% identical).
Diseases named in the same sentence as MRPL15 in open-access papers:
MRPL15 is named in the same sentence as 25 diseases in open-access papers, as found by Europe PMC text mining. Sharing a sentence is not in itself a finding about the gene and the disease. The quoted sentences say what the papers report.
ovarian carcinoma (10 papers, 2021 to 2025). A malignant neoplasm originating from the surface ovarian epithelium. "High MRPL15 expression is associated with an advanced stage and a poor prognosis in ovarian cancer patients." (PMID 39859078, 2025). "It has been reported that the expression of MRPL15 is significantly increased in ovarian cancer patients and is associated with poor prognosis of patients." (PMID 39684863, 2024). "MRPL15 has shown prognostic potential in both breast and ovarian cancers, with expression correlating with recurrence and risk of metastatic disease." (PMID 39354291, 2024). "Mitochondrial ribosomal protein L15 (MRPL15) is observed highly expressed in epithelial ovarian cancer and is also associated with poor patient overall survival." (PMID 35754835, 2022). "MRPL15 is highly expressed in epithelial ovarian cancer and is associated with poor overall survival of patients." (PMID 33934540, 2021). "To explore the relationship between overexpression of MRPL15 and somatic mutations in ovarian cancer, we analyzed genes with somatic mutation in the high‐ and low‐MRPL15‐expression groups." (PMID 33934540, 2021). "We found that MRPL15 expression in ovarian cancer was significantly negatively correlated with its methylation (Pearson's r = −0.1187, p = 0.0086), suggesting that abnormal expression of MRPL15 in ovarian cancer occurs because of the loss of methylation." (PMID 33934540, 2021). "Somatic mutations associated with MRPL15 were explored using TCGA ovarian cancer data." (PMID 33934540, 2021). "High expression of MRPL15 in ovarian cancer may be associated with its amplification and hypomethylation." (PMID 33934540, 2021). "Notably, these expression and prognosis verification results are highly consistent with our online database analysis results, indicating the potential of MRPL15 as a diagnostic and prognostic marker for ovarian cancer." (PMID 33934540, 2021). "Kaplan-Meier survival analysis shows that high expression of MRPL15, MRPL36, MRPL39, and MRPS16 is significantly associated with poorer OS in ovarian cancer patients." (PMID 40371222, 2025). "TCGA ovarian cancer data, gene set enrichment analysis, and Enrichr were used to explore the mechanism of MRPL15 in ovarian cancer." (PMID 33934540, 2021). "By combining the results obtained using TCGA ovarian cancer database, GTEX database, Oncomine, cBioPortal, and Kaplan Meier‐Plotter, we found that MRPL15 plays a most significant role in ovarian cancer among the six MRPs." (PMID 33934540, 2021). "This suggests that any increase in the MRPL15 copy number in ovarian cancer can partly result in high expression of MRPL15." (PMID 33934540, 2021). "Eighty‐one patients with epithelial ovarian cancer were included divided into two groups: a high‐MRPL15‐expression group (++/+++) and low‐MRPL15‐expression group (−/+)." (PMID 33934540, 2021). "Only MRPL15 was highly expressed in ovarian cancer in both Oncomine analyses and the combined analyses of TCGA and GTEX." (PMID 33934540, 2021). "For example, MRPL15 is a new prognostic indicator and therapeutic target for epithelial ovarian cancer." (PMID 34868337, 2021). "To further explore the mechanism of overexpression of MRPL15 in ovarian cancer, we explored the relationship between MRPL15 expression and copy number variation, methylation, and somatic mutation." (PMID 33934540, 2021). "The high positive rate of MRPL15 expression in patients with epithelial ovarian cancer at FIGO stage III/IV (93.02%) was significantly higher than in patients at FIGO stage I/II (76.32%; p = 0.035)." (PMID 33934540, 2021). "For example, in ovarian cancer, MRPL15 (mitochondrial ribosomal protein 15) is suggested as a prognostic indicator and therapeutic target, or XRCC2 repairing mtDNA damage in hepatocellular carcinoma." (PMID 35008363, 2021). "MRPL15 was highly expressed and amplified in ovarian cancer and was related to the poor prognosis of patients." (PMID 33934540, 2021).
ovarian carcinoma (continued). "GSE13876, which includes 157 patients with serous ovarian cancer at an advanced stage, was selected to verify the prognostic value of MRPL15 in ovarian cancer." (PMID 33934540, 2021). "In GSE51088, the expression of MRPL15 in epithelial ovarian cancer was significantly higher than that in ovarian borderline tumors (p = 2.5e‐06), ovarian benign tumors (p = 7.3e‐11), and normal ovarian tissues (p < 2.22e‐16)." (PMID 33934540, 2021). "Notably, TISIDB showed that MRPL15 may also be associated with ovarian cancer progression." (PMID 33934540, 2021). "Mechanism analysis indicated that MRPL15 plays a role in ovarian cancer through pathways such as the cell cycle, DNA repair, and mTOR 1 signaling." (PMID 33934540, 2021). "After analyzing the expression and prognostic impact of these MRPs in ovarian cancer, we selected MRPL15, which is the gene most closely correlated with the tumorigenesis and prognosis of ovarian cancer, for further verification and mechanism analysis." (PMID 33934540, 2021). "Next, we analyzed the relationship between the expression of MRPL15 and tumor immune infiltration in ovarian cancer." (PMID 33934540, 2021). "This indicates that MRPL15 can be used as a marker for immunophenotyping of patients with ovarian cancer and for predicting the prognosis of patients." (PMID 33934540, 2021). "In TCGA ovarian cancer database, we found that MRPL15 expression was significantly related to the difference in the immune subtype of ovarian cancer, and its expression in C3 ovarian cancer was significantly lower than in the other three types (p < 0.0001)." (PMID 33934540, 2021). "Using Oncomine for further analysis, we found that the copy number of MRPL15 in ovarian cancer was significantly higher than that in blood and normal ovaries in TCGA Ovarian2 Statistics." (PMID 33934540, 2021). "Using TCGA Ovarian Statistics to compare 586 cases of serous ovarian cancer with eight cases of normal ovarian tissues, MRPL15 was found to be significantly overexpressed in ovarian cancer (p = 2.13e‐8, fold‐change =2.485)." (PMID 33934540, 2021). "Our results indicate that MRPL15 expression was significantly reduced in C3 ovarian cancer, which has the best prognosis." (PMID 33934540, 2021). "The results showed that MRPL36 and MRPL15 had the highest genetic variation rate in ovarian cancer, with gene amplification as the most common type." (PMID 33934540, 2021). "In conclusion, analysis of the Oncomine and TCGA databases showed that MRPL15 is overexpressed in ovarian cancer, showing the most significant expression difference among the six MRPs." (PMID 33934540, 2021). "Further analysis of the copy number variation data in TCGA showed that with increasing gene copy number amplification, MRPL15 expression was significantly increased in ovarian cancer (p < 0.05)." (PMID 33934540, 2021). "MRPL15 is upregulated in ovarian cancer, a phenomenon which may be partially due to the amplification and hypomethylation of MRPL15." (PMID 39859078, 2025). "Similarly, Xu and colleagues (2021) demonstrated the potential use of MRPL15 as an ovarian cancer prognostic biomarker and therapeutic target." (PMID 39354291, 2024). "Therefore, MRPL15 can be used as a new prognostic biomarker and therapeutic target for epithelial ovarian cancer." (PMID 39684863, 2024). "We next examined the possible mechanism of MRPL15 overexpression in ovarian cancer." (PMID 33934540, 2021). "Finally, the relationship between MRPL15 expression and immune subtype, tumor‐infiltrating lymphocytes, and immune regulatory factors was analyzed using TCGA ovarian cancer data and TISIDB." (PMID 33934540, 2021). "In addition, the prognostic value of MRPL15 was verified in epithelial ovarian cancer by analyzing our patient samples." (PMID 33934540, 2021). "Additionally, MRPL15 showed the lowest expression in C3 ovarian cancer and was correlated with proliferation of CD8+ T cells and dendritic cells as well as TGFβR1 and IDO1 expression." (PMID 33934540, 2021).
ovarian carcinoma (continued). "In summary, MRPL15 may be a candidate biomarker and novel therapeutic target for epithelial ovarian cancer." (PMID 33934540, 2021). "Interestingly, from previous enrichment analysis of the MRPL15 pathway, we predicted that MRPL15 promotes the development of ovarian cancer through the mTOR pathway." (PMID 33934540, 2021). "In addition, poorly differentiated ovarian cancer samples showed higher expression of MRPL15 compared to well/moderately differentiated ovarian cancer samples (p = 0.019)." (PMID 33934540, 2021). "Notably, MRPL15 has the highest expression level in ovarian cancer and is closely related to cell cycle, DNA repair, and mTOR1 signaling pathways, potentially promoting the occurrence and development of ovarian cancer through gene amplification and hypomethylation." (PMID 40371222, 2025). "MRPL15 may play a role in ovarian cancer through cell cycle or DNA repair pathways." (PMID 39684863, 2024). "MRPL15 may be a prognostic indicator and therapeutic target for ovarian cancer." (PMID 33934540, 2021). "In addition to participating in basic functions related to mitochondrial oxidative phosphorylation, high expression of MRPL15 in ovarian cancer may be related to cell cycle, DNA repair, DNA replication, and the mTOR signaling pathway." (PMID 33934540, 2021). "Therefore, high expression of MRPL15 in ovarian cancer may occur partially because of copy number variation and hypomethylation." (PMID 33934540, 2021). "Comparison of the relationship between these genes and the prognosis of ovarian cancer showed that overexpression of MRPL15, MRPL36, and MRPS31 may lead to poor OS and PFS in patients with ovarian cancer, among which MRPL36 showed the greatest prognostic significance." (PMID 33934540, 2021). "In addition, MRPL15 exhibited the highest expression in ovarian cancer." (PMID 33934540, 2021). "To gain comprehensive insight into the mechanism of MRPL15 in ovarian cancer, we performed KEGG, BioCarta, and Reactome pathway enrichment analyses for 791 genes correlated with MRPL15 screened from the cBioPortal database." (PMID 33934540, 2021). "Six MRPs (MRPL10, MRPL15, MRPL36, MRPL39, MRPS16, and MRPS31) related to HE4 in ovarian cancer were selected." (PMID 33934540, 2021). "Further IHC and GEO validation results also showed that the expression of MRPL15 in ovarian cancer was significantly increased and was significantly related to advanced FIGO stage, poor differentiation, and poor OS in ovarian cancer patients." (PMID 33934540, 2021). "MRPL10, MRPL15, MRPL36, MRPL39, and MRPS16 were highly expressed in ovarian cancer, whereas MRPS31 showed the opposite tendency." (PMID 33934540, 2021). "Four studies suggested that the expression of MRPL15 was significantly increased in ovarian cancer, whereas one study concluded that the expression of MRPS31 was significantly decreased in ovarian cancer." (PMID 33934540, 2021). "In addition, MRPL15 had a high variation rate and was significantly related to the OS and PFS of patients with ovarian cancer." (PMID 33934540, 2021). "According to univariate Cox regression analysis, MRPL15 expression (HR = 2.119, p = 0.039), FIGO stage (HR = 1.651, p = 0.004), and differentiation (HR = 1.411, p = 0.027) were significantly correlated with the OS of patients with epithelial ovarian cancer." (PMID 33934540, 2021). "In addition, the expression of MRPL15 in ovarian cancer was increased in advanced stages but not significantly (Spearman's correlation: 0.111, p = 0.054)." (PMID 33934540, 2021). "Therefore, MRPL15 may lead to immune tolerance of ovarian cancer by participating in the downstream mTOR pathway of IDO1, thereby promoting the progression of ovarian cancer." (PMID 33934540, 2021). "In addition, because of its close correlation with HE4, MRPL15 may interact with HE4 to promote the oncogenesis and development of ovarian cancer." (PMID 33934540, 2021). "However, studies have not focused on MRPL15 in ovarian cancer." (PMID 33934540, 2021).
breast carcinoma (6 papers, 2021 to 2025). "Previous research has shown that MRPL15 can be used as a companion diagnostic marker to determine which breast cancer patients might benefit most from clinical therapy." (PMID 41334450, 2025). "Previous studies demonstrated that MRPL15 is significantly associated with poor prognosis of patients with breast cancer and that it can be used with other MRPs to establish a model to predict the prognosis of and drug efficacy for patients with estrogen receptor‐positive breast cancer." (PMID 33934540, 2021). "MRPL15 has been reported to have a predictive value in breast cancer metastasis and can promote Burkitt lymphoma growth." (PMID 34026630, 2021). "In particular, in breast cancer, uL15m (MRPL15), uL13m (MPRL13) and mL54 (MPRL54) protein levels correlated with cancer recurrence, distant metastasis and prognosis." (PMID 34071057, 2021). "presented evidence revealing that MRPL15 has predictive value in breast cancer distant metastasis." (PMID 34026630, 2021). "Previous research has shown that both MRPL15 and MRPS23 can be selected as companion diagnostics, to decide which breast cancer patients might benefit most from clinical therapy (Sotgia, Fiorillo & Lisanti, 2017)." (PMID 34603851, 2021).
lung carcinoma (4 papers, 2020 to 2025). "High expression of both MRPL15 mRNA and protein is associated with a poor prognosis in lung cancer patients." (PMID 39859078, 2025). "Taken together, MRPL15 can serve as an independent risk factor for survival and prognosis of lung cancer patients." (PMID 34026630, 2021). "Upregulation of MRPL15 is observed in many types of cancer, including lung cancer, CRC, and gastric cancer." (PMID 39859078, 2025). "Correlation between MRPL15 expression and clinicopathological characteristics in lung cancer patients." (PMID 34026630, 2021). "MRPL15 is a member of mitochondrial ribosomal proteins whose abnormal expression is related to tumorigenesis in lung cancer, epithelial ovarian cancer and so on." (PMID 34777466, 2021). "The lung cancer patients with high MRPL15 expression had a poor OS than those with low MRPL15 expression." (PMID 34026630, 2021). "IHC results further validated the high MRPL15 expression and its prognostic potential in lung cancer." (PMID 34026630, 2021). "Furthermore, the expression and prognostic value of MRPL15 in lung cancer were validated via immunohistochemistry (IHC) assays." (PMID 34026630, 2021). "Secondly, MRPL15 is overexpressed in lung cancer patients and predicts poor OS." (PMID 34026630, 2021). "Furthermore, IHC results further confirmed the high MRPL15 expression and its prognostic potential in lung cancer." (PMID 34026630, 2021). "Only a recent study showed that MRPL15 was associated with progression in lung adenocarcinoma, but the prognostic value and regulatory mechanisms of MRPL15 in lung cancer are still unknown." (PMID 34026630, 2021). "Similarly to MRPL15, upregulation of MRPL19 is observed in many types of cancer, including lung cancer, CRC, and gastric cancer." (PMID 39859078, 2025).
Alzheimer disease (2 papers, 2021 to 2025). A progressive, neurodegenerative disease characterized by loss of function and death of nerve cells in several areas of the brain leading to loss of cognitive function such as memory and language. "As a risk gene and potential biological target of Alzheimer’s disease (AD), MRPL15 also plays an important role in regulating immune cells in AD." (PMID 41334450, 2025).
lung adenocarcinoma (2 papers, 2021 to 2025). A carcinoma that arises from the lung and is characterized by the presence of malignant glandular epithelial cells. "Finally, by integrating the results of PPI network analysis and one-way COX regression analysis, we identified six RBPs that are both DEGs and associated with lung adenocarcinoma prognosis—IGF2BP3, SNRPE, GAPDH, MRPL12, MRPL15, and INTS8, with IGF2BP3 being the most differentially expressed." (PMID 40801655, 2025).
lymph node metastasis (2 papers, 2021). "IHC results further validated the findings: Firstly, MRPL15 expression is related to lymph node metastasis." (PMID 34026630, 2021). "Our results indicated that MRPL15 expression is strongly related to lymph node metastasis (P = 0.028)." (PMID 34026630, 2021).
non-small cell lung carcinoma (2 papers, 2021 to 2023). A group of at least three distinct histological types of lung cancer, including non-small cell squamous cell carcinoma, adenocarcinoma, and large cell carcinoma. "However, the prognostic value and regulatory mechanisms of MRPL15 in non-small-cell lung cancer (NSCLC) remain unclear." (PMID 34026630, 2021). "Additionally, MRPL15, which belongs to the same family as MRPL13, promotes the malignant progression of non-small cell lung cancer and affects the inhibitory effect of the immune system on tumor cells." (PMID 37827692, 2023).
colon cancer (1 paper, 2021). "Finally, the GTPase ERAL1, mitochondrial ribosomal proteins ERAL1, MRPL11, MRPL15, MRPL30, MRPL37, MRPL40, and MRPL52 were determined to be hub proteins with a commonly down-regulated trend in four berberine-treated colon cancer cell lines." (PMID 33806918, 2021).
colon tumors (1 paper, 2021). "Based on the transcriptome data from the GEPIA database, seven hub proteins identified in this study were over-expressed in colon tumors at the transcriptional level, and MRPL15, 30, and 37 were significantly over-expressed in colon tumor samples (a two-fold change with p-value < 0.05 as a cut off)." (PMID 33806918, 2021).
diabetic retinopathy (1 paper, 2025). "In addition, a recent study has confirmed that MRPL15 is significantly correlated with diabetic retinopathy." (PMID 41334450, 2025).